KRAS (KRas proto-oncogene, GTPase)
Diseases named in the same sentence as KRAS in open-access papers (continued):
Sharing a sentence is not in itself a finding about the gene and the disease.
lung cancer (continued). "Nonetheless, proliferation of KRAS-wild type lung cancer cells seemed not to be affected by trametinib." (PMID 38643157, 2024). "One of the most relevant examples of lung cancer are the EGFR and KRAS oncogenes." (PMID 38612473, 2024). "We found that HOXC10 may serve as a novel biomarker of KRAS-mutant lung cancer bone metastasis, implying the multifaceted role of HOXC10 in KRAS-mutant lung cancer bone metastasis and broadening the application of HOXC10-based therapy." (PMID 39191757, 2024). "As the bone metastasis of lung cancer cells can lead to osteolytic lesions and induction of osteoclastogenesis, we next tested whether HOXC10 drives KRAS-mutant lung cancer cells to trigger osteoclastogenesis." (PMID 39191757, 2024). "LKB1 silencing is frequently observed in patients with KRAS-driven lung cancer, and such patients exhibit decreased overall survival and are more refractory to current therapeutic treatments than in LKB1-proficient KRAS-driven lung cancers." (PMID 39213022, 2024). "Preinduced primary preosteoclasts were exposed to conditioned medium from H441 and A549 KRAS-mutant lung cancer cells with or without HOXC10 knockdown." (PMID 39191757, 2024). "Furthermore, TBK1 activity is selectively essential for the survival of cancer cells with mutant KRAS, identified in a systematic synthetic lethal RNAi screening in NCI-H23 cells, a lung cancer cell line expressing mutant KRAS." (PMID 39279883, 2024). "Our results contradict recent reports showing that KD did not prevent cachexia in a KRAS‐driven murine lung cancer model, a heterotopic C26 colon cancer model or the autochthonous genetically engineered KPC PDAC model." (PMID 38632714, 2024). "Unlike lung cancers with mutated EGFR and ALK expressions, KRAS has long been considered a challenging therapeutic target, even regarded as “undruggable”." (PMID 38734764, 2024). "For example, EGFR mutant lung cancers may express higher levels of MHC I molecules, while KRAS mutant cancers may express lower levels of CD47 and MHC I molecules." (PMID 38483480, 2024). "Nevertheless, our study finds that MH suppressed both KRAS-mutated (A549) and KRAS wild-type (H1299) cells, indicating that the effect of MH on lung cancer is independent of KRAS inhibition." (PMID 39518013, 2024). "Resistance to sotorasib in KRAS G12C lung cancer is due to genetic/non-genetic mechanisms and can be alleviated by carfilzomib." (PMID 37831779, 2023). "In KRAS G12D driven murine models of lung cancer, YAP activation may compensate for KRAS depletion and enable continued tumor growth upon KRAS G12D inhibition." (PMID 37277530, 2023). "In one study on the clinical outcome of pembrolizumab versus chemotherapy in lung cancer patients, it was observed that the treatment outcomes appeared to be comparable irrespective of the presence of STK11, KEAP1, or KRAS mutations." (PMID 38136385, 2023). "For example, MICAL3 negatively correlates with KRAS dependency in our model and is frequently enriched in non-smoker related lung cancer." (PMID 37141389, 2023). "Other analyses defined the oncogenic driver roles of various KRAS mutant forms and found that G12C is a real major driver oncogene in lung cancer, unlike G12D/V which are only “mini-drivers,” cooperating with other mutant oncogens." (PMID 38239281, 2023). "Depletion of CRAF has been shown to decrease tumor size without notably affecting MAPK signaling in KRAS-driven lung cancer." (PMID 38111008, 2023). "In addition, inhibition of GTPase KRas, Sir‐2, ALK5 and β‐catenin were shown when TQ was applied to lung cancer cells." (PMID 37697969, 2023).
lung cancer (continued). "Finally, in lung cancer patients high UHRF1 expression is anti-correlated with TSG expression and predicts worse outcomes for patients with KRAS mutant tumors." (PMID 37407562, 2023). "CRISPR technology has been successfully applied to implement the editing and modulation of numerous oncogenes such as epidermal growth factor receptor (EGFR), KRAS, focal adhesion kinase (FAK), metabotropic glutamate receptor 8 (GRM8), SMAD3/4, and MET in lung cancer." (PMID 38188023, 2023). "Consistent with our results, another small drug agonist of KRAS (which binds the GTP/GDP-binding pocket of KRAS and leads to the accumulation of GTP-KRAS) was previously reported to induce the apoptotic and autophagic cell death of lung cancer cells." (PMID 36614192, 2023). "Moreover, we used 2 human lung cancer cell lines, H358 (KRASG12C) and SK-LU-1 (KRASG12D), to further illustrate the potential regulation of CD47 by KRAS." (PMID 36413402, 2023). "Similar compounds discovered by additional groups have led to the rapid development of direct KRAS G12C inhibitors, the most clinically advanced of which are MRTX849 (adagrasib) and AMG510 (sotorasib), both of which are now FDA-approved for use in lung cancer." (PMID 37141389, 2023). "Thus, we conducted a correlation study between FGF11 and EGFR (19DEL, L858R), EGFR (Exon 20ins), KRAS (G12C), ALK, ROS1, BRAF, NTRK1/2/3, MET, and RET, which are all recommended by the NCCN guidelines for the diagnosis of nonsmall cell lung cancer." (PMID 37250453, 2023). "Collectively, our data suggest that the combination of SHP2 and TGFβ inhibitors is effective at reversing SHP2 inhibitor-induced senescence and decreasing survival in KRAS mutant lung cancer models, likely independent of apoptotic mechanisms." (PMID 38102334, 2023). "Regarding the molecular profile of lung cancer, only one of our ILD patients with non-squamous NSCLC (7%) had a targetable genetic mutation (KRAS G12C), which tended to be lower than that in the non-ILD group (21.5%), without being significant (p = 0.26)." (PMID 37568692, 2023). "As of now, no studies have definitively categorized KRAS subtype variations as independent prognostic indicators for ICI responses in lung cancer patients." (PMID 37954616, 2023). "Finally, from the subset of genes that were anticorrelated with both KRAS and UHRF1 expression we selected genes whose increased expression was protective (hazard ratio <1) in KRAS mutant lung cancer patients." (PMID 37407562, 2023). "Intriguingly, this study also identified a negative association between tobacco smoke and the G12D substitution in KRAS; in other words, KRAS G12D is more common among the lung cancers of non-smokers." (PMID 37004719, 2023). "Broad inhibition of kinases of the ERBB family by neratinib has been shown to suppress KRAS G12D mutant-driven lung tumors and enhance the potency of MEK inhibition by trametinib in a cre-inducible immunocompetent mouse model of autochthonous lung cancer." (PMID 37314501, 2023). "G12C, which is well-known for its high detection rate in lung cancer and the recent development of its inhibitor sotorasib, was observed only in 2.2% of KRAS mutant PDAC patients, and none in ACC, ASC, and ACP patients." (PMID 37029223, 2023). "In addition, a number of recent studies have shown that LLPS is involved in the signaling activation of lung cancer carcinogenic pathways such as EGFR, ALK and KRAS." (PMID 37580790, 2023).
lung cancer (continued). "KRAS has long been considered ‘undruggable’, and the management of KRAS-addicted lung cancer is considered the same as that of non-oncogene-addicted cancer." (PMID 36741723, 2022). "Interestingly, it has been reported that KRAS-mutant NSCLC cells are dependent on XPO1-mediated nuclear export, rendering XPO1 a druggable vulnerability in KRAS-mutant lung cancer." (PMID 35573474, 2022). "Twelve (18%) patients had KRAS mutation, two patients were EGFR mutation‐positive (3%), one patient had a BRAF mutation (2%) and no patient had lung cancer that was ALK mutation‐positive." (PMID 34196124, 2022). "Importantly, we found that combinational inhibition of KRAS, NF-κB, and PD-1 effectively shrank autochthonous KrasG12D/ZNF24−/− lung cancers in transgenic mouse model." (PMID 36457047, 2022). "Interestingly, our results showed that the risk of VTE in ROS1 rearrangements(ROS1+) patients is 2.63-fold greater than that in ROS1- patients, and the odds of VTE in ROS1+ lung cancer were higher than ALK+, EGFR+ and KRAS+ cohorts in the univariate analysis." (PMID 36300098, 2022). "KRAS-driven and only bioinformatic analysis of the TCGA database shows that CDC73 mRNA expression was positively correlated with distant metastasis and unfavorable prognosis of lung cancer." (PMID 36430528, 2022). "For example, the combined actions of endogenously expressed mutant KRAS and modestly deregulated MYC expression led to NK cell‐mediated immune escape through inhibition of IFN‐I pathways in pancreatic ductal adenocarcinoma and lung cancer." (PMID 35253368, 2022). "This might be explained by the influence of KRAS on AA concentrations in the TIF, making chemo-naïve lung cancer cells dependent on de novo asparagine synthesis to sustain proliferation." (PMID 35857457, 2022). "We then tested whether NF-κB inhibitor synergized KRAS inhibitors in treating Zno/K* patients on EKVX-shZNF24, a lung cancer cell line harboring wildtype (WT) but super active KRAS." (PMID 36457047, 2022). "Importantly, BCL6 was functionally required for KRAS-mutant lung tumorigenesis and tumor growth, as the genetic or pharmacological inhibition of BCL6 significantly impeded the growth of KRAS-mutant lung cancer in preclinical mouse models." (PMID 36377663, 2022). "In this context, the activity of oncogenic KRAS is modulated by the iRhom2-dependent release of ERBB ligands, thus placing the cytoplasmic domain of iRhom2 as a central component of a positive feedback loop in lung cancer cells." (PMID 35971826, 2022). "Nowadays, first-line standard treatment of KRAS-mutant lung cancer is based on chemotherapy, combined with or without ICIs." (PMID 35887766, 2022). "There is increasing evidence that KRAS-mutant NSCLC does not simply represent a homogeneous subgroup of lung cancer." (PMID 35887766, 2022). "Unlike in other mutant lung cancers, in KRAS-mutant tumors, additional genomic alterations frequently occur." (PMID 36291146, 2022). "Recently, KRAS G12C inhibition was shown to upregulate interferon signaling, enhanced CD8 + T-cell infiltration and synergism with immune checkpoint inhibition in immunogenic murine lung cancer models." (PMID 36284306, 2022). "Given that the KRAS/MAPK/ELK1 axis directly regulates BCL6 expression, we next investigated whether activated BCL6 promoted KRAS-mutant lung cancer." (PMID 36377663, 2022). "This work is particularly relevant because it establishes a link between copper ability to modulate autophagy and the KRAS pathway: in a mouse model of KrasG12D-driven lung cancer, the binding of copper to ULK1 is mandatory for autophagy and to support tumorigenesis in KRAS." (PMID 36291728, 2022). "In addition to canonical RAF-MEK-ERK signaling inhibitors, direct KRAS inhibitors are under development and KRASG12C inhibitors are approved for the treatment of lung cancers." (PMID 36534167, 2022).
lung cancer (continued). "It is possible that KRAS might regulate KIF4A in a cell type-specific manner, and this particular regulation in the context of lung cancer requires further elucidation." (PMID 36499051, 2022). "In contrast, the lung cancer cells line harbouring an EGFR-mutation, but not a KRAS mutation, H1975 (KRAS-wild type) does not show inhibited colony growth by specific KRAS-inhibition." (PMID 35220407, 2022). "FTIs showed in vitro activity in KRAS-mutant lung cancer in mice, but its clinical activity has not been confirmed in NSCLC clinical trials." (PMID 36012655, 2022). "In addition, depletion of iRhoms induced a similar decrease in amphiregulin release in the KRAS mutant NSCLC cells lines NCI-H358 and NCI-H1792, demonstrating the conserved function of iRhoms in promoting growth factor signalling in lung cancer cell lines." (PMID 35971826, 2022). "KRAS, ROS1, ALK, and EGFR are the main biomarkers affecting clinical practice of lung cancer." (PMID 36260870, 2022). "Especially in lung cancer, various targeted therapies have been developed, ranging from EGFR-TKIs and BRAF, ALK, ROS, RET, MET, TRK1, and HER2 inhibitors, to more recent developments in KRAS inhibitors." (PMID 34359729, 2021). "This synthetic lethal interaction was observed only in lung cancer, not in colon or pancreatic cancer, pointing to a different tissue specific dependency of KRAS signaling." (PMID 33777798, 2021). "Finally, using publicly available datasets, significant up-regulation of both KRAS and USP39 was found in lung cancer patients where high expression levels of USP39 were also associated with short survival." (PMID 34065438, 2021). "To investigate fusion genes in lung cancer, we analysed RNA-sequencing data of 29 patients with lung adenocarcinoma (NCCLUAD) who lacked activating mutations in KRAS or EGFR." (PMID 33204025, 2021). "GATA2 was significantly downregulated in both human and mouse lung tumors and its further suppression was not an effective treatment for KRAS mutant lung cancer." (PMID 34093794, 2021). "In lung cancer patients with mutant KRAS, ICI therapy showed lack of benefit, in contrast to the wild-type group of tumors." (PMID 34164344, 2021). "Co-occurring genetic events were frequently observed in KRAS-mutant lung tumors, unlike other oncogene-driven lung cancers." (PMID 33435990, 2021). "As of today, differences in the effectiveness of chemotherapy, antiangiogenic therapy, targeted therapy, or immunotherapy among lung cancer patients with different KRAS mutant subtypes are not known." (PMID 35070984, 2021). "The exosomes secreted by lung cancer cells that enrich various proteins, such as EGFR, KRAS, claudins, and RAB-family proteins that promote the development of lung cancer, can be effective biomarkers for the early diagnosis of lung cancer and the basis of targeted therapy." (PMID 34769444, 2021). "In this study, we found that MitoQ and MitoTEMPO administration had no impact on the number of primary tumors and lymph metastases in mice with BRAF-induced malignant melanoma and no impact on tumor burden in mice with KRAS-induced lung cancer." (PMID 33499262, 2021). "Patients with KRAS mutations showed the lowest incidence for VTE among the analyzed driver genes, and both KRAS and EGFR mutations were proved no significant relation with VTE risks in patients with lung cancer." (PMID 33996610, 2021).
lung cancer (continued). "During the past 20 years, important progress has been made in our understanding of the molecular pathogenesis of lung cancer, whose malignant transformation has been demonstrated to result from the accumulation of genetic aberrations such as in EGFR, KRAS, and ALK." (PMID 33288886, 2021). "Indeed, it has been demonstrated in preclinical trials that Vitamin C is enough to sensitize KRAS-mutant cells to cetuximab in CRC and Erlotinib in lung cancer, both in vivo and in vitro." (PMID 34359657, 2021). "Moreover, we determined the expression of PGK1 with several typical genetic alteration events in lung cancer, including EGFR mutants, KRAS mutants, and ALK fusions in The Cancer Genome Atlas (TCGA) clinical cohort." (PMID 34091600, 2021). "Unlike EGFR-mutant lung cancer, KRAS oncoproteins are largely undruggable, with the very recent exception of the KRASG12C allele." (PMID 34309585, 2021). "Unlike patients with lung cancer harboring EGFR mutations or ALK translocations, diseases for which targeted agents typically achieve 60 to 80% response rates, KRAS G12C inhibitors such as sotorasib and adagrasib typically yield 40 to 50% response rates." (PMID 34680229, 2021). "Though our pre-clinical findings were contained within the KP syngeneic model, the increase in PD-L1 expression in mutant KRAS;STK11 (KL) lung cancer cell lines suggest that our proposed therapeutic strategy may be extended to KL lung cancer subtypes." (PMID 33972557, 2021). "Studies have shown that YAP1 expression is induced by KRAS activation, aerobic glycolysis, GNAS, and the cancer upregulated gene (CUG) 2 exhibiting upregulated expression in lung cancer which could increase the expression of YAP1." (PMID 33648545, 2021). "In addition, we identify many other candidate EGFR-, KRAS-, and RIT1 dependencies that should be further explored as drug targets for lung cancer therapy." (PMID 34373451, 2021). "The KRAS, NRAS and HRAS genes have mutational spectra which differ in lung cancer for smoker’s vs non-smokers." (PMID 34521464, 2021). "This suggests that the classical KRAS-PI3K-AKT pathway is not essential for acquired resistance to sotorasib, whereas KRAS-independent PI3K activation favors such resistance in lung cancer cells." (PMID 34607583, 2021). "Studies have shown significant differences in mutation patterns and frequencies of KRAS and EGFR genes between smokers and never smokers with lung cancer." (PMID 33381603, 2020). "Despite the encouraging preclinical results showing significant antitumor activity and favorable safety profile in mice and monkeys bearing KRAS-mutant lung cancer, the first phase I clinical trial (NCT03101839) failed, possibly because AZD4785 targets both mutant and wild type KRAS protein." (PMID 32548736, 2020). "Since the larger fraction of lung cancer patients is KRAS wild type, it is likely that methylated HOXA9 can be found in lung cancer patients irrespective of KRAS status." (PMID 33322500, 2020). "As far back as 1990, KRAS mutation was described as a negative prognostic marker for both OS and disease‐free survival (DFS) in lung cancer." (PMID 33022831, 2020). "It is interesting and reassuring that these recently published antagonistic reports do not rule out IKKβ as a relevant target in KRAS-induced lung cancer." (PMID 32823550, 2020). "Therefore, we believe that the combined detection of EZH2 with EGFR, KRAS, and BRAF has more advantages in the diagnosis and treatment of lung cancer." (PMID 33299862, 2020). "Nonetheless, MMP9 expression regulation by the KRAS/IKKβ pathway in these cells is likely unimportant, as targeting either KRAS or IKKβ in both lung cancer cell lines did not affect MMP9 enzymatic activity." (PMID 32823550, 2020).